MOB1B (MOB kinase activator 1B)
Description:
Activator of LATS1/2 in the Hippo signaling pathway which plays a pivotal role in organ size control and tumor suppression by restricting proliferation and promoting apoptosis. The core of this pathway is composed of a kinase cascade wherein STK3/MST2 and STK4/MST1, in complex with its regulatory protein SAV1, phosphorylates and activates LATS1/2 in complex with its regulatory protein MOB1, which in turn phosphorylates and inactivates YAP1 oncoprotein and WWTR1/TAZ. Phosphorylation of YAP1 by LATS1/2 inhibits its translocation into the nucleus to regulate cellular genes important for cell proliferation, cell death, and cell migration. Stimulates the kinase activity of STK38L.
Synonyms: MOB4A; MOBKL1A; MATS2
Tractability: PROTAC: ubiquitination databases record sites on it.
Gene: Protein-coding gene on chromosome 4 (70,902,326 to 71,022,449, forward strand). Ensembl gene ENSG00000173542.
Subcellular location: Cytoplasm; Nucleus
Subcellular location (Human Protein Atlas): Nucleoli; Nucleoplasm; Cytosol
Pathways (Reactome):
Signal Transduction: Signaling by Hippo
Gene Ontology:
Molecular function: kinase activator activity; kinase binding; protein binding; protein serine/threonine kinase activator activity; protein kinase activator activity
Biological process: hippo signaling; regulation of protein autophosphorylation
Cellular component: cytoplasm; cytosol; extracellular exosome; nucleolus; nucleoplasm; nucleus
Genetic constraint (gnomAD): Loss-of-function variants: 12 observed, 15.67 expected, observed/expected ratio (o/e) 0.77, 90% interval 0.49 to 1.24. The upper end of that interval is the gene's LOEUF score, 1.24, which puts it in group 5 of 6, group 1 being the genes least tolerant of losing a copy. Missense variants: 177 observed, 190.27 expected, observed/expected ratio (o/e) 0.93, 90% interval 0.82 to 1.05. Synonymous variants: 48 observed, 61.25 expected, observed/expected ratio (o/e) 0.78, 90% interval 0.62 to 1.
Homologues: Orthologues: dog MOB1B (100% identical), guinea pig MOB1B (99% identical), rat Mob1b (99% identical), mouse Mob1b (99% identical), rabbit MOB1B (98% identical), chimpanzee MOB1B (98% identical), zebrafish mob1ba (98% identical), zebrafish mob1bb (96% identical), tropical clawed frog mob1b (94% identical), Drosophila melanogaster mats (88% identical). Paralogues in human: MOB1A (96% identical), MOB3B (55% identical), MOB3A (54% identical), MOB3C (49% identical), MOB2 (42% identical), MOB4 (22% identical).
Diseases named in the same sentence as MOB1B in open-access papers:
MOB1B is named in the same sentence as 15 diseases in open-access papers, as found by Europe PMC text mining. Sharing a sentence is not in itself a finding about the gene and the disease. The quoted sentences say what the papers report.
breast carcinoma (1 paper, 2020). "In this study, MOB kinase activator 1A (MOB1A) was detected in stage 2, while both MOB1A and MOB1B were detected in stage 3 breast cancer samples." (PMID 31945087, 2020).
chordoma (1 paper, 2022). Chordomas are rare malignant tumors arising from embryonic remnants of the notochord in axial skeleton. "Five regulators of this pathway (TAOK1, TAOK2, MOB1A/B, and LATS1) were significantly suppressed in chordoma samples and two of them are predicted targets for upregulated miRNAs (TAOK1 for miR-142, and MOB1B for miR-148a and miR-182)." (PMID 36033338, 2022).
head and neck cancer (1 paper, 2023). A primary or metastatic malignant neoplasm affecting the head and neck.
myeloma (1 paper, 2020). "We found that increased level of MOB1B demonstrated a trend for better overall survival in patients with myeloma." (PMID 32154065, 2020). "Using MOB1B‐specific shRNA knockdown and YAP/TAZ genetic overexpression, we have further demonstrated an important role of MOB1B‐YAP/TAZ pathway in PINK1‐mitophagy‐mediated myeloma cell migration." (PMID 32154065, 2020). "However, MOB1B‐specific shRNA knockdown restored at least in part myeloma cell transwell migration that was attenuated by PINK1 overexpression." (PMID 32154065, 2020). "To further confirm whether MOB1B has a direct role in PINK1‐mediated myeloma cell migration, we knocked down MOB1B using MOB1B‐specific shRNA in the PINK1 overexpression MM cells and examined its effects on the expression of YAP and TAZ and myeloma cell transwell migration." (PMID 32154065, 2020).
prostate carcinoma (1 paper, 2015). A carcinoma that arises from epithelial cells of the prostate gland. "We noted that many Hippo pathway SNPs (one in MST1, three in STK3, two in LATS2, one in MOB1B, and six in WWTR1; total 13 out of 75) genotyped in our prostate cancer patient cohort were not in Hardy-Weinberg equilibrium (HWE)." (PMID 25707771, 2015).
systolic heart failure (1 paper, 2024). Heart failure caused by abnormal myocardial contraction during systole leading to defective cardiac emptying. "For example, forced expression of a constitutively active form of Yap in the adult heart stimulated cardiac regeneration and improves contractility after MI, while Hippo kinase pathway (Mst1, Lats2 and Mob1b) deficiency reversed systolic heart failure after MI." (PMID 38396885, 2024).
cancer (3 papers, 2012 to 2024). A tumor composed of atypical neoplastic, often pleomorphic cells that invade other tissues. "Since there is no antibody available to distinguish MOB1A and MOB1B, we analyzed their expressions by RT-PCR in a panel of pancreatic normal and cancer cells, which showed that MOB1A mRNA level is 5–15 fold higher than MOB1B in these cells." (PMID 31659153, 2019).
tumor (2 papers, 2022 to 2023). "MOB1B is identified as a tumor suppressor, and it interacts with and activates LATS1/2 kinase, which is critical for fully activating LATS1." (PMID 37076815, 2023).
MOB1B also shares sentences with these, for which no sentence is quoted: head and neck squamous cell carcinoma (1 paper); liver cancer (1); melanoma (1); meningioma (1); myocardial infarction (1); Obesity (1); schwannoma (1).